GAS6 (growth arrest specific 6)
Diseases named in the same sentence as GAS6 in open-access papers (continued):
Sharing a sentence is not in itself a finding about the gene and the disease.
viral infection (16 papers, 2015 to 2024). "Growth arrest-specific 6 (Gas6) is a member of the vitamin K-dependent protein family, which is closely associated with viral infection." (PMID 35682869, 2022). "Gas6 may act as a modulator of inflammation, regulating the immune response and limiting the inflammation and tissue damage associated with viral infection." (PMID 38745659, 2024). "Notably, these pathways, which are associated with viral infection, involve the GAS6 gene." (PMID 35682869, 2022). "The versatile role of the Gas6/TAM system in viral infection is supported by its involvement, not only in mediating or facilitating viral entry, but also in other major functions." (PMID 37630598, 2023). "GAS6 mRNA was decreased in the MSCs stimulated with recombinant IL-1β, TNF-α, TGFβ1 (produced by MSC), and PDGBB (produced by endothelial cells) at 6 h, while poly I:C, known to mimic viral infections, increased GAS6 expression." (PMID 37958918, 2023). "It is well known that serum proteins such as Protein S and Gas6 enhance some enveloped-virus infections in macrophages." (PMID 35746720, 2022). "Together, transcriptome analysis identified hundreds of genes that are probably under the regulation of ALKBH5, including GAS6, which is a viral infection-related gene that we selected for further analysis." (PMID 35682869, 2022). "To confirm that AXL directly induces viral infection independently of its ligand GAS6 or Protein S in serum, we performed control experiments and found that GAS6 and Protein S are dispensable in AXL-induced SARS-CoV-2 virus pseudotype infection." (PMID 33420426, 2021). "To further confirm the role of Gas6 in mediating virus infection, we also measured virus replication in SC pretreated with an anti-Gas6 antibody specific for the Axl binding domain of Gas6." (PMID 31311882, 2019). "Remarkably, the unique neurotropism of ZIKV provides an alternative strategy for the treatment of GBM in adults given the overexpression of MSI1 as well as AXL and its ligand Gas6 which are important for the viral infection." (PMID 31824472, 2019). "Studies of our and other research groups also showed that 1) Gas6 can mediate viral infection more efficiently than protein S and 2) Axl and Tyro 3 mediate viral infection more efficiently than Mer." (PMID 31638994, 2019). "Our studies revealed that Protein S and Gas6 mediate the binding step of virus infection by binding to envelope PtdSer and TAM receptors expressed on target cells." (PMID 31638994, 2019). "The receptor binds to ZIKV through growth arrest-specific 6 (Gas6) which acts as a cofactor to promote viral infection." (PMID 31824472, 2019). "Of particular interest is growth arrest-specific 6 (GAS6), which appears to link viral infection and MI." (PMID 26193668, 2015). "This last observation could be related to the ability of Gas6 to bind to PtdSer residues, which is emerging as an interesting feature in viral infection." (PMID 36674471, 2023). "Consistently, Gas6 may represent an early response mechanism to limit viral infection damages and subsequent cytokine storm." (PMID 35531477, 2022). "Specifically, the VP1 protein of SV40 could structurally mimic Gas6 to directly interact with AXL to enhance viral infection." (PMID 32172658, 2020). "Six genes were closely associated with viral infection, namely, LY6E, receptor-type tyrosine-protein phosphatase S (PTPRS), neurogenic locus notch homolog protein 3 (NOTCH3), tripartite motif containing 56 (TRIM56), ring finger protein 135 (RNF135), and growth arrest-specific 6 (GAS6)." (PMID 38169284, 2024). "Viral infection can also influence TAM receptors expression and Gas6 production." (PMID 38745659, 2024). "Moreover, the Gas6 TAM pathway is involved in viral response, including thus EBV infection, increasing during a viral infection." (PMID 38745659, 2024).
viral infection (continued). "These in vitro studies highlighted that knocking down Axl or its addition in the soluble recombinant form to cell culture is effective in reducing the viral infection of pulmonary epithelial cells, while its biological ligands (Gas6 and protein S) do not bind to SARS-CoV-2." (PMID 36674471, 2023).
multiple sclerosis (15 papers, 2013 to 2025). A progressive autoimmune disorder affecting the central nervous system resulting in demyelination. "The circulating protein Gas6 is a promising therapy to promote remyelination in people with multiple sclerosis." (PMID 40778495, 2025). "Increased expression of GAS6 has been described in the retina of an experimental model of multiple sclerosis, and its involvement in neuronal and glial cell survival has been determined in multiple sclerosis models." (PMID 39000104, 2024). "We aimed to investigate the role of Gas6/TAM in neurodegenerative processes in multiple sclerosis (MS)." (PMID 39673059, 2024). "Higher levels of GAS6 in cerebrospinal fluid of multiple sclerosis patients correlated with lower relapse severity." (PMID 39000104, 2024). "Fortunately, this deficiency in efferocytic clearance is treatable with recombinant TGF-β, which restored expression of MERTK and Gas6 to basal levels in multiple sclerosis patients." (PMID 34065321, 2021). "A study on cuprizone-induced demyelination model (adopted as a model of multiple sclerosis) revealed that the deletion of Gas-6/Axl signaling leads to prolonged neuroinflammation with axonal damage and consistent demyelination." (PMID 30949117, 2019). "This immune-regulatory role links Gas-6 to autoimmune disorders, more specifically to the pathogenesis of multiple sclerosis (MS)." (PMID 30949117, 2019). "The effect of Gas6 on expression of 84 different MS-related genes was examined in the adult optic nerve, using the Mouse Multiple Sclerosis PCR array (Qiagen)." (PMID 27630207, 2016). "While Gas6 positively correlated with soluble Axl and Mer in normal tissue, an inverse negative correlation was observed between Gas6 and soluble Axl and Mer in established multiple sclerosis lesions." (PMID 39974615, 2025). "There is also a decrease in Gas6 expression in the brains of patients with multiple sclerosis." (PMID 34065321, 2021). "Based on these premises, in the present study we measured CSF and plasma Gas6 protein during a relapse of multiple sclerosis in relation to relapse clinical features and severity scores as Kurtzke-Functional-System (FS), to verify their usefulness as a biomarker of disease course." (PMID 23781120, 2013). "Thus, the ability of Gas6 to suppress GM-CSF induction over a prolonged period could provide a novel avenue to therapeutically target GM-CSF in disorders such as multiple sclerosis, where GM-CSF plays a critical role in mediating the disease pathology." (PMID 34943789, 2021). "Therefore, we aimed to verify whether cerebrospinal-fluid (CSF) Gas6 concentration may represent a biomarker of disease activity in multiple sclerosis." (PMID 23781120, 2013). "Recent findings have further related Gas6 and TAM receptors to neuroinflammation in general and, specifically, to multiple sclerosis (MS)." (PMID 27801848, 2016).
fibrosis (14 papers, 2018 to 2025). the formation of excess fibrous connective tissue in an organ or tissue in a reparative or reactive process. "Gas6/alb showed high diagnostic accuracy for the detection of significant (≥F2: AUC 0.805) to advanced fibrosis (≥F3: AUC 0.818), and was superior to Fib-4 for the detection of cirrhosis (F4: AUC 0.897 vs. 0.878)." (PMID 37532736, 2023). "Mice harboring a deletion of Axl or Gas6 show decreased susceptibility to steatosis, steatohepatitis, and fibrosis." (PMID 37532736, 2023). "In conclusion, Gas6/alb shows a high accuracy to detect significant to advanced fibrosis and cirrhosis, and predicts severity of liver disease including CSPH." (PMID 37532736, 2023). "As Gas6 levels were found to be highly elevated in advanced fibrosis and cirrhosis and progression of cirrhosis, we conclude that excess of bioactive Gas6 is available to bind cognate Axl receptors." (PMID 37532736, 2023). "Specifically, sAxl concentration had already augmented in individuals with compensated cirrhosis compared to initial fibrosis, while Gas6 levels had increased markedly in the decompensated cirrhosis group." (PMID 31583026, 2019). "Among individuals with different degrees of NAFLD (steatosis/fibrosis/cirrhosis), only cirrhotic patients displayed increased Gas6 and MERTK serum levels." (PMID 31583026, 2019). "GAS6 was predicted to interact with two lncRNAs that were clinically proven to affect DN fibrosis." (PMID 41233312, 2025). "Recently, the potential diagnostic value of Gas6 and its albumin ratio was evaluated in patients with biopsy-proven chronic liver diseases, revealing that Gas6/albumin ratio possesses high accuracy in detecting advanced fibrosis and cirrhosis and predicts the severity of liver disease." (PMID 38298195, 2024). "In this study, we investigated the Axl ligand Gas6 and Gas6/alb for its value to accurately detect significant to advanced fibrosis, cirrhosis, and HCC, as well as its potential to predict decompensated cirrhosis, ESLD, CSPH, and transplant-free survival in a large multicenter cohort." (PMID 37532736, 2023). "Fibrosis is a physiological response to tissue damage; therefore, it is reasonable to postulate that this protective effect of Gas6 and its receptors may be played at the expense of the development of fibrosis and scarring." (PMID 31614787, 2019). "However, serum Gas6 levels have been shown to be elevated in patients with advanced fibrosis and cirrhosis as well as in HCC patients." (PMID 31583026, 2019). "The question is whether the analysis of Gas6/sAxl levels in patients’ blood can be used to diagnose advanced fibrosis/cirrhosis as well as HCC." (PMID 30567378, 2018). "In particular, the role of Gas6/Axl signaling in liver fibrosis and HCC requires further elucidation in order to test several hypotheses." (PMID 30567378, 2018). "Furthermore, Gas6 knockout (Gas6-/-) mice fed with CDE diet or treated with carbon tetrachloride (CCl4) have shown an improvement of steatohepatitis and fibrosis compared to control mice." (PMID 38298195, 2024). "Our previous results identified the GAS6/TAM pathway as a relevant mechanism activated in patients suffering from MASH, which could be prevented by targeting AXL as demonstrated in experimental animal models of fibrosis and MASH." (PMID 38817615, 2024).
glioma (14 papers, 2009 to 2024). A benign or malignant brain and spinal cord tumor that arises from glial cells (astrocytes, oligodendrocytes, ependymal cells). "While mutations in EFEMP2, ADAM10, SERPINH1, ADAM15, GAS6 and TNXB were detected only in patients with glioma grade 3, mutations in LTBP2, DCN, CRELD1 and HAPLN3 were observed only in patients with glioma grade 4, GBM." (PMID 38272115, 2024). "The interaction of GAS6-AXL has been found in glioma while we identified several novel combinations in our study which need to be validated by the experiments in glioma." (PMID 37456890, 2023). "•The receptor tyrosine kinase (RTK) Axl and its ligand Gas6 are critically involved in the pathogenesis of high-grade glioma (HGG)." (PMID 29876303, 2018). "The extracellular domain of Axl (sAxl) and Gas6 were found in the peri-tumoral edema and blood of animals as well as in human glioma tissue." (PMID 29876303, 2018). "Invasiveness has been correlated with the expression of Axl, and Gas6-dependent signaling through Axl has been shown to promote invasion of glioma cells." (PMID 19888345, 2009). "However, the biological functions of Gas6/TAM in schwannoma and glioma have been demonstrated through the inhibition of Gas6/TAM signalling." (PMID 28333143, 2017). "The N32 glioma was less responsive to the blocking of Gas6 and AXL signaling." (PMID 19558675, 2009). "Our results show an increased inhibition of tumor growth by the NPC with the addition of either antibodies to these proteins, which point towards an implication of the importance for Gas6-AXL signaling in promoting tumor growth in vitro in the syngeneic rat glioma models." (PMID 19558675, 2009). "Gas6 is the principal ligand for all three TAM receptors and has also been found to be overexpressed in glioma." (PMID 25980499, 2015). "We identified several targets involved in glioma growth and migration, specifically CXCL1, CD81, TPT1, Gas6 and AXL proteins." (PMID 19558675, 2009). "Specific candidates like follistatin and the Gas6/AXL system, point towards future experiments evaluating them in more detail as targets for future therapy of gliomas." (PMID 19558675, 2009). "In studies of gliomas, dominant-negative Axl lacking the intracellular domain interfered with cell migration, and in GN11 cells Gas6 signaling downstream of Axl was implicated in cell migration." (PMID 21569627, 2011). "This implies that targeting the Gas6/AXL pathway in gliomas might not only have direct effects on tumor proliferation signals but could have secondary effects by decreasing the vascularization of the tumor and may present a good target for glioma therapy." (PMID 19558675, 2009). "Therefore, it may well be that exclusive inhibition of the AXL/Gas6 axis, as it has been discussed for gliomas and other cancer types, might not suffice to prevent AXL activation in GBMs." (PMID 28881571, 2017).
idiopathic pulmonary fibrosis (14 papers, 2019 to 2025). Idiopathic pulmonary fibrosis (IPF) is a nonneoplastic pulmonary disease that is characterized by the formation of scar tissue within the lungs in the absence of any known cause. "Increased Gas6 and Axl expression have previously been observed in lung samples and fibroblast cultures from Idiopathic Pulmonary Fibrosis (IPF) patients." (PMID 41155824, 2025). "GAS6/AXL pathways were associated with fibrogenesis in CLD and idiopathic pulmonary fibrosis, respectively, and were reversed by BGB324." (PMID 31822557, 2020). "In a bleomycin-induced pulmonary fibrosis model, Gas6 −/− knock out (KO) led to a significant decrease in hydroxyproline content when compared with wild-type mice at Day 14 after bleomycin exposure." (PMID 31614787, 2019). "The authors also assessed the in vivo role of Gas6/TAM receptors using two experimental models of pulmonary fibrosis." (PMID 31614787, 2019). "While Gas6 may exert anti-fibrotic effects by regulating epithelial and immune cell responses in the context of acute lung injury or idiopathic pulmonary fibrosis, its function within the TME is likely to differ." (PMID 40940956, 2025). "However, one recent study using mouse models has shown that Gas6 signaling can alleviate pulmonary fibrosis by inhibiting epithelial–mesenchymal transition and fibroblast activation." (PMID 40940956, 2025). "Furthermore, Gas6-deficient mice exhibited an intensified EMT in ATII cells and more activated myofibroblast-like phenotypes, consequently aggravating pulmonary fibrosis after BLM treatment." (PMID 38578518, 2024). "Here, we investigated whether growth arrest-specific protein 6 (Gas6) plays a protective role in lung fibrosis via suppression of the EMT and fibroblast activation." (PMID 38578518, 2024). "In our investigation, we showed that the lack of Gas6 exacerbated lung fibrosis by causing an increased EMT process and fibroblast activation 14 day post-BLM treatment compared with that in WT control mice." (PMID 38578518, 2024). "Importantly, the defensive function of endogenous Gas6 in BLM-induced lung fibrosis was confirmed through investigations performed using mice lacking Gas6." (PMID 38578518, 2024). "Although many studies have focused on the roles of the Gas6/TAM system in lung pathophysiology, mostly in tumor development and resistance to cancer therapies, the number of those assessing the contribution of the Gas6/TAM axis to the development of pulmonary fibrosis is still very limited." (PMID 37630598, 2023). "Moreover, both Gas6 deficiency and TAM inhibition attenuated pulmonary fibrosis in murine models." (PMID 41155824, 2025). "In patients with Idiopathic Pulmonary Fibrosis (IPF), Gas6, Axl, and Tyro3 were elevated compared to the healthy control, and phosphorylated Axl was higher in rapid progressors versus slow progressors." (PMID 39057085, 2024). "Collectively, these data suggest Gas6-deficient mice exhibit exaggerated BLM-induced EMT and fibroblast activation, leading to further accumulation of collagen and intensified fibrosis, indicating a protective role of Gas6 against the progression of pulmonary fibrosis." (PMID 38578518, 2024). "Additionally, Gas6 and Axl expressions were observed to increase in lung tissues and fibroblasts obtained from patients affected by idiopathic pulmonary fibrosis, a severe chronic fibrotic disease of the lung which shares several clinical and pathophysiological features with CTD-ILD." (PMID 32454903, 2020). "Others, on the other hand, have demonstrated that Axl and/or Gas6 activity leads to the stimulation of pulmonary fibroblasts and TGF-β production in individuals with idiopathic pulmonary fibrosis." (PMID 38774866, 2024).
idiopathic pulmonary fibrosis (continued). "Thus, our hypothesis was confirmed because Gas6 signaling is essential for preventing or blocking the progression of pulmonary fibrosis through inhibition of the EMT process and alveolar epithelial cell apoptosis as well as concomitantly restraining fibroblast activation." (PMID 38578518, 2024). "Collectively, these findings suggest that Gas6/Axl signaling events consequently mediate rGas6-induced inhibition of the EMT process and fibroblast activation in BLM-induced lung fibrosis." (PMID 38578518, 2024). "Moreover, the Gas6/TAM axis is also known to regulate fibrotic response triggered by chronic inflammation in many clinical conditions, such as liver cirrhosis and pulmonary fibrosis." (PMID 35531477, 2022). "Growth arrest-specific 6 (GAS6) and protein S are also vitamin K-dependent proteins, which are important regulators of tissue repair after injury and may be involved in the pathogenesis of pulmonary fibrosis." (PMID 40290659, 2025). "In this study, we explored if injecting murine recombinant Gas6 (rGas6) suppresses the EMT process and apoptosis in primary ATII cells and concomitantly inhibits fibroblast activation to protect against the progression of pulmonary fibrosis in mice treated with BLM." (PMID 38578518, 2024). "However, whether Gas6 suppresses alveolar epithelial type II (ATII) cells in the process of EMT and inhibits fibroblast activation to prevent lung fibrosis in vivo is still unknown." (PMID 38578518, 2024). "Therefore, Gas6/Axl signaling events play a potential role in inhibition of EMT process and fibroblast activation via COX-2-derived PGE2 and PGD2 production, ultimately preventing the development of pulmonary fibrosis." (PMID 38578518, 2024). "Taken together, our findings suggest that Gas6/Axl/Akt pathway possibly leads to the increased COX-2 transcriptional induction as well as PGE2 and PGD2 secretion to protect against the development of the EMT phenotype in ATII cells and the myofibroblast phenotype during BLM-induced lung fibrosis." (PMID 38578518, 2024). "Furthermore, a recent study also demonstrates that targeting Gas6 and TAM receptors with either specific antibodies directed at Gas6 or Axl or with small-molecule TAM inhibitors attenuates the activation of pulmonary fibroblasts in idiopathic pulmonary fibrosis." (PMID 34829903, 2021).